CD47 (CD47 molecule)
Diseases named in the same sentence as CD47 in open-access papers (continued):
Sharing a sentence is not in itself a finding about the gene and the disease.
tumor (continued). "The first among these checkpoints is CD47, an anti-phagocytic factor that serves as a “don’t eat me” signal by tumor cells to escape phagocytic clearance by myeloid cells." (PMID 36959214, 2023). "In the tumor samples, CD47 and p-STAT3 expression levels were much higher in the KRASMUT patients than in the KRASWT patients." (PMID 36413402, 2023). "Spatial CRISPR screening confirmed tumor-facilitating effects of immune checkpoints (PD-L1 and CD47), and also identifies tumor composition, organization, and immune infiltration in the TME, following Socs1 and TGFBR2 KO lesion." (PMID 36797756, 2023). "CD47 is expressed highly on a variety of cancer cells and functions as a key antiphagocytic protein which maintains tumor cells’ resistance to host immune surveillance." (PMID 36882399, 2023). "Weissman’s team found that almost all cancer cells had high levels of CD47, and the large amount of CD47 expression interacts with macrophages’ SIRPα, which the tumor clearance ability of macrophages." (PMID 37484024, 2023). "In theory, bispecifics should focus the therapeutic effects of CD47 blockade more specifically on tumor cells while minimizing adverse effects that result from ubiquitous CD47 expression." (PMID 37958404, 2023). "For example, dual-specific CAR-T cells targeting a second additional antigen, such as CD30 or CD47, have been developed to potentiate the anti-tumor activity of anti-STn CAR-T cells." (PMID 37854601, 2023). "Our findings confirm that CD47/SIRPα is an important myeloid checkpoint that regulates neutrophil killing of tumor cells." (PMID 37444515, 2023). "Our study successfully developed a tumor-selective, pH-dependent anti-CD47 antibody (BC31M4) that safely confers strong therapeutic effects against solid tumors." (PMID 36650558, 2023). "As the most studied antiphagocytosis signal in the tumor microenvironment, CD47 has been shown to be overexpressed on the surface of many types of cancer cells." (PMID 36413402, 2023). "A second study that investigated immunomodulatory molecules in LCSC obtained from lymph node aspirates, confirmed that CD47 expression was higher on cancer stem cells compared to mature tumor cells." (PMID 37958404, 2023). "On the other hand, other strategies to enhance the anti-tumour responses of TAMs include restoring their phagocytic capacity by blocking the “don’t eat me” signal of CD47-SIRPα." (PMID 37894344, 2023). "As a immune checkpoint, CD47 can attach to signal regulatory proteins α(SIRPα) on the surface of macrophages in the tumor microenvironment and deliver “don’t eat me” messages in order to evade immune surveillance." (PMID 37546397, 2023). "Anti-CD47 antibodies have exhibited potent antitumor efficacy in many human tumor xenograft models, specifically by promoting the tumoricidal activity of macrophages, and similar results were observed in our study." (PMID 36650558, 2023). "Pep-20 was able to block the interaction between CD47 and SIRPα, thereby enhancing the macrophage-mediated phagocytosis of tumor cells." (PMID 37108657, 2023). "Increasing evidence has suggested that blocking CD47–SIRPα interaction promotes the phagocytosis of cancer cells, resulting in the suppression of tumor growth and progression." (PMID 37894750, 2023). "The best-studied function of CD47-SIRPα is the induction of tumor immune evasion during cancer immunotherapy." (PMID 36882399, 2023). "The PEG/Se layer was disrupted when modified OMVs were delivered in solid tumor under radiation-triggered control, and the CD47 nanobody exerted the function to block CD47-mediated inhibition of efficient tumor cell phagocytosis by macrophages." (PMID 37896250, 2023). "Taken together, these data suggested that KRAS signaling can suppress miR-34a expression via the PI3K/STAT3 axis, which in turn relieves miR-34a–dependent repression of CD47, leading to escape from innate immune surveillance and tumor progression." (PMID 36413402, 2023).
tumor (continued). "Cancer‐expressed CD47 was found to be involved in tumour immune escape through interaction with signal regulatory protein‐α (SIRP‐α), expressed by TAMs, being able to quench phagocytosis in a preclinical model of acute leukaemia." (PMID 37654003, 2023). "By interacting with immune checkpoint receptors and SIRPα on immune cells, CD47 can suppress anti-tumor immunity and promote immune evasion." (PMID 38188674, 2023). "The CD47-SIRPα pathway is a phagocytosis checkpoint in macrophages and other innate immune cells, and CD47 has been verified to be a promising therapeutic target due to its antiphagocytic function in tumor cells." (PMID 36882399, 2023). "6MW3211 was designed with high binding affinity to hPD-L1 and low affinity to hCD47, which allows 6MW3211 to preferentially bind to hPD-L1 expressing tumor cells followed by CD47/SIRPα signaling disrupting." (PMID 36593962, 2023). "CD47-targeted therapies, including mAbs, small molecule inhibitors, and nanotherapeutics, have been developed to block the CD47-SIRPα interaction and enhance phagocytosis of cancer cells by myeloid cells, thereby promoting anti-tumor immunity." (PMID 38188674, 2023). "Apart from immune‐independent tumour suppression, we further verified the effect of innate and adaptive anti‐tumour immunity through blocking the SIRPα/CD47 and PD‐1/PD‐L1 pathway in vitro." (PMID 37974395, 2023). "Because of their determination of tumor cell phagocytosis, antibodies that block the CD47-SIRPα axis show great application prospects." (PMID 37691932, 2023). "As an innate immune checkpoint, CD47 on tumour cells can interact with the signal regulatory protein SIRPα on the surface of macrophages and send a ‘don't eat me’ signal to assist tumour cells to escape immune surveillance." (PMID 37974395, 2023). "SIPRα on macrophages binds with CD47 to resist proengulfment signals, but how the downstream signal of SIPRα controls tumor-infiltrating macrophages (TIMs) is still poorly clarified." (PMID 36626230, 2023). "Small interfering RNA targeting CD47 gene (CD47 siRNA, siCD47) silences CD47 expression, promotes the recognition and clearance of tumor cells by the immune system, and enhances the anti-tumor immune response dependent on T cells." (PMID 37063284, 2023). "This study showed synergistic tumor inhibition by a combination of radiotherapy plus anti-CD47 and anti-HER2 immunotherapy." (PMID 36900399, 2023). "Preclinical studies have shown that blocking CD47 with antibodies or oncolytic viruses can convert TAMs to a pro-inflammatory phenotype and enhance phagocytosis of tumor cells in GBM models." (PMID 37474548, 2023). "Flow cytometry analysis of the tumor tissue revealed that the treatment with NP/siCD47 and NP/R848/siCD47 weakened the expression of CD47 in line with the in vitro experiment." (PMID 37063284, 2023). "Blocking CD47 in tumor cells expressing CD47 increased TAM frequencies in double-transgenic ATC mice." (PMID 37007127, 2023). "Our development of a tumor-selective, pH-dependent anti-CD47 antibody confirms that the acidic tumor microenvironment is an exploitable characteristic for effective deployment of antibodies to treat solid tumors." (PMID 36650558, 2023). "The CD47-SIRPα axis is the first macrophage-related checkpoint identified for tumor immunotherapy in the 21st century." (PMID 37484024, 2023). "Expression of CD47 Y286F inhibited tumor growth, prolonged mouse survival time, and reduced CD47 expression in tumor tissues, as detected by IHC analysis." (PMID 37541303, 2023). "In macrophages, integrin activation was shown to be inhibited by positioning of SIRPa in the phagocytic synapse after ligation of tumor-expressed CD47." (PMID 38138970, 2023). "The peritoneal tumor cell–killing model was utilized to assess the role of neddylated SHP2 in the CD47/SIRPα axis in vivo." (PMID 36626230, 2023). "Previous studies have shown that anti-CD47 inhibited the proliferation, invasion and migration of tumor cells." (PMID 37171006, 2023).
tumor (continued). "Anti-CD47 therapy showed significant anti-tumor activity compared to control and was superior to Olaparib (p < 0.001)." (PMID 37468567, 2023). "Testing this therapy on human glioblastoma cell lines and xenografts, they showed that the addition of anti-CD47 led to increased tumor-cell phagocytosis in both M1 and M2 macrophages, but this increase was more prominent in M1 macrophages." (PMID 37987252, 2023). "In a variety of immunocompetent mouse tumor models, including ovarian cancer, breast cancer, and pancreatic cancer, treatment with anti‐CD47 antibodies stimulated macrophage phagocytosis in vitro and suppressed tumor growth in vivo." (PMID 37706196, 2023). "Immune checkpoint proteins, including Programmed Death 1 (PD-1) and its ligands PD-L1 and PD-L2, Lymphocyte Activation Gene 3 (LAG-3), CD200, Cytotoxic T Lymphocyte Activator 4 (CTLA-4), and CD47, are involved in tumor immunology and benefit tumor growth." (PMID 37626420, 2023). "The effectiveness of CUDC101 and IR780 provide synergistic anti-tumor effects via photosensitizer-based photodynamic therapy and drug-induced CD47 suppression, demonstrating reprogramming to M1-type TAMs." (PMID 36903458, 2023). "CPT1A and CD47 are highly expressed in radiotherapy resistant GBM tumors, and inhibition of CPT1A can result in decreased CD47 expression and increased macrophage phagocytosis of tumor cells." (PMID 37033619, 2023). "Studies demonstrated that anti-CD47 mAbs stimulate DCs to phagocytose tumor cells, which is followed by antigen presentation to CD8+ T cells to trigger an anticancer adaptive immune response." (PMID 38033495, 2023). "The SAP nanofibers are then able to block subsequent interaction of CD47 and SIRPalpha, promoting the phagocytosis of tumor cells." (PMID 36937769, 2023). "Tumor-specific antibodies that engage Fc receptors on macrophages should also induce phagocytosis, particularly when combined with CD47 blocking antibodies or the use of CD47−/− tumor cell lines." (PMID 37074910, 2023). "The results showed that, compared with that in mice of the sh-NC group (control), tumor bioluminescence was significantly low in mice of the sh-CD47 group (bioluminescence difference = -3.82e8 photos/s in shCD47 1#, -2.02e8 in shCD47 2#, **P < 0.01)." (PMID 36860925, 2023). "One study showed that blocking the CD47‐ signal regulatory proteins α (SIRPα) axis between tumor cells and phagocytes enhanced the phagocytosis of tumor cells by innate immune cells." (PMID 36999977, 2023). "CD47 is an important anti-phagocytosis signal, which can prevent the phagocytosis of tumor cells by macrophages via binding to ligand signal regulatory protein α (SIRPα) on macrophages." (PMID 37334368, 2023). "Except for the interaction of CD47 on tumor cells with SIRPα on neutrophils, the knowledge about immune checkpoint molecules on neutrophils is limited." (PMID 37346044, 2023). "Our results suggest that, compared to an anti-CD47 monotherapy, combination therapies designed both to selectively target tumor cell killing and to promote adaptive immune responses should be more efficacious for treating solid tumors in patients." (PMID 36650558, 2023). "In both KRASMUT and KRASWT patients, we found that CD47 was highly expressed in the tumor samples compared with their normal counterpart samples." (PMID 36413402, 2023). "By competing with CD47, it inhibits CD47-induced macrophage phagocytosis and enhances antibody-dependent phagocytosis of macrophages to eliminate tumor cells." (PMID 37484024, 2023). "CD47 is a transmembrane protein that is widely expressed in all types of cells, and is especially overexpressed in most tumor cells." (PMID 37108657, 2023). "One approach to address this challenge is to reduce the affinity of bsAbs for CD47 while maintaining strong blocking of the CD47-SIRPα interaction and increasing the affinity for binding to another tumor antigen." (PMID 38125492, 2023).
tumor (continued). "The CD47 protein in lay terms is a “don’t eat me signal” that inhibits macrophage phagocytosis of tumor cells which overexpress this protein." (PMID 37987252, 2023). "Tumor cells and macrophages were co-cultured and treated with anti-CD47 antibody (B6H12) or IgG1 isotype control in this study." (PMID 37171006, 2023). "The expression of MHC-I protein by tumor cells was shown to correlate with the level of tumor resistance to anti-CD47 therapy." (PMID 38033495, 2023). "On the surface of tumor cells, CD47 binds to SIRPα, inhibiting macrophage-mediated phagocytosis, which is an important means of tumor immune escape." (PMID 37049910, 2023). "Doxorubicin, cisplatin, and the EGFR tyrosine kinase inhibitor, Osimertinib, have been found to potentiate the efficacy of CD47 blockade by upregulating pro-phagocytic signals in preclinical tumor models." (PMID 37958404, 2023). "Conversely, CD47 functions in the tumor microenvironment can depend on the engagement of either SIRPα or TSP1." (PMID 36768931, 2023). "First, signal regulatory protein α (SIRPα) expressed on macrophages can bind to CD47, which is highly expressed on tumor cell membranes, to enhance the "don't eat me" signal." (PMID 36794651, 2023). "Confirming screen robustness, sgRNAs targeting genes required for T cell function were depleted from the tumor, including Tap1, B2m, CD47, Jak1, and Jak3." (PMID 38099496, 2023). "By exploiting the "Don't eat me" signal, cancer cells utilize CD47's overexpression to evade immune cell surveillance and clearance, making CD47 a potential target for novel anti-tumor therapies." (PMID 37822610, 2023). "CD47-targeted immunotherapy approaches aim to enhance anti-tumor immunity and improve clinical outcomes by disrupting the “don’t eat me” signal between CD47 (on cancer cells) and SIRPα (on myeloid cells)." (PMID 38188674, 2023). "Accordingly, many trials are evaluating CD47 blockade in combination with chemotherapy, targeted therapy, or other IOs known to induce “eat me” signals, increase tumor immunogenicity, and/or stimulate tumor immunity." (PMID 37958404, 2023). "We then determined the interaction between CD47 on tumor cells and SIRPα on macrophages in vitro and in vivo." (PMID 36959204, 2023). "Lastly, CD47 antagonists can promote tumor cell death, reduce tumor cell proliferation, and prevent tumor cell migration." (PMID 36726125, 2023). "Various tumor types overexpress CD47, enabling evasion of macrophage‐mediated phagocytosis, making the SIRPα‐CD47 interaction an attractive therapeutic target." (PMID 37206279, 2023). "Lastly, an assessment of a NSCLC cohort with 98 samples revealed that CD47 expression on tumor cells was positively correlated with FOXP3+ T cells, but was not correlated with PD-L1 or CD68+ macrophage markers." (PMID 37958404, 2023). "CD47, identified as a self-marker on RBCs to prevent their clearance by macrophages, is overexpressed in most types of cancer cells and is considered a tumor phagocytosis checkpoint molecule." (PMID 37894750, 2023). "As such, most mechanistic investigations of CD47 blockade have focused on characterizing phagocytosis and adaptive tumor immunity that follows." (PMID 37958404, 2023). "Genetically engineered CD19-CAR T cells to secrete anti-CD47 scFv effectively enhance the polyfunctionality and tumor killing function of CAR T cells, uplifting their persistence and immune activity and facilitating their differentiation into naive phenotypes." (PMID 37781520, 2023). "CD47 expression in HCC cells is correlated with the poor overall survival of patients with HCC and antibody-mediated targeting CD47 was shown to inhibit tumour growth in mouse models of HCC." (PMID 37894344, 2023). "Confirmation of the interplay between the CD47/SIRPα pathway and NEDD8 was substantiated by decreased deneddylation in CD68+ macrophages from tumor tissue organoids treated with anti-CD47 antibody." (PMID 36787255, 2023).
tumor (continued). "When CD47 is expressed on fibroblasts, it can activate Tregs and promote their immunosuppressive function, leading to a reduced anti-tumor immune response." (PMID 38188674, 2023). "Antibody blockade or antisense knockdown of CD47 increases T cell receptor-dependent killing of tumor cells by CD8 T cells in vitro and in vivo." (PMID 36768931, 2023). "Tumor cells overexpress CD47 in many cancer types, disguising them as healthy cells and avoiding phagocytosis." (PMID 37706196, 2023). "Another study found that the efficacy of anti-CD47 therapies are enhanced separately by both Irradiation and temozolomide administration by decreasing tumor growth and increasing survival times in mouse models." (PMID 37275361, 2023). "Another targeted approach involves CD47, a widely expressed transmembrane protein which interacts with signal regulatory protein-alpha on the surface of macrophages to protect tumor cells from phagocytosis." (PMID 36969049, 2023). "We use the nanodrug delivery system to deliver CD47 siRNA to tumor tissues and tumor cells, which can effectively improve the targeted regulation of CD47 molecules in tumor cells." (PMID 37063284, 2023). "Employing CD47-overexpressed T-EVs instead of anti-CD47 antibodies to block CD47/SIRPα signal has the advantage that T-EVs can carry therapeutics to kill tumor cells around macrophages, thus “killing two birds with one stone”." (PMID 37283792, 2023). "Some “don’t eat me” signal blockades, such as RF231(a fully human anti-CD47), can not only promote CD47-mediated death signaling in tumor cells but also triggers FcγR-mediated phagocytosis of tumor cells." (PMID 37345054, 2023). "Blocking CD47 with anti-CD47 antibody (B6H12) suppressed tumor cell growth, motility and promoted macrophage-mediated phagocytosis in IOMM-Lee cells in vitro." (PMID 37171006, 2023). "Cordycepin has been documented to exhibit anti-tumor effects through the facilitation of apoptosis and autophagy, as well as the inhibition of CD47 expression to augment anti-tumor immunity." (PMID 38178862, 2023). "Several prior publications suggest that overexpression of CD47 by tumor cells inhibits phagocytosis by macrophages, allowing cancer cells to evade immune surveillance, and this is associated with tumor progression in several cancer types." (PMID 36598153, 2023). "In vivo study revealed that HAC NVs had better tumour penetration than monoclonal antibodies and higher binding affinity to CD47 and PD‐L1 on tumour cells compared with the NVs expressing wild‐type fusion protein." (PMID 37974395, 2023). "CD47 is another immunoglobulin highly expressed on the surface of tumor cells, which can inhibit macrophage-mediated phagocytosis by binding to its major ligand signal regulatory protein α, thereby negatively regulating anti-tumor immunity." (PMID 37600785, 2023). "Interference with CD47 inhibition of macrophages using antibodies has been found to slow tumor implantation and growth in preclinical models." (PMID 37484024, 2023). "Treatment with magrolimab induces CD47 blockade resulting in significantly decreased primary tumor growth, decreased lung metastasis and prolonged animal survival in the established humanized model." (PMID 37868989, 2023). "When activated, CD47 results in the inhibition of phagocytosis of cells and the production of a “don’t eat me signal” on tumor cells." (PMID 38001669, 2023). "Treatment with a monoclonal anti-CD47 antibody delays the tumor growth in HNSCC in immunocompetent mice, affecting the AKT pathway." (PMID 36829496, 2023). "Inhibition of isoQC blocks the interaction between CD47 and SIRPα, leading to constrained tumor growth." (PMID 38125492, 2023). "Blockade of the CD47-SIRPα signal has been shown to stimulate phagocytosis, leading to tumor cell elimination." (PMID 36911370, 2023). "6MW3211 effectively blocked both PD-1/DP-L1 and CD47/SIRPα signaling and promoted macrophage phagocytosis of tumor cells." (PMID 36593962, 2023).